PCYOX1 (prenylcysteine oxidase 1)
Description:
Prenylcysteine oxidase that cleaves the thioether bond of prenyl-L-cysteines, such as farnesylcysteine and geranylgeranylcysteine. Only active against free prenylcysteines and not prenylcysteine residues within prenylated proteins or peptides (By similarity). Involved in the final step in the degradation of prenylated proteins, by degrading prenylcysteines after the protein has been degraded.
Synonyms: KIAA0908; PCL1
Tractability: Antibody: UniProt predicts a signal peptide or a membrane-spanning region. PROTAC: ubiquitination databases record sites on it; its protein half-life has been measured.
Gene: Protein-coding gene on chromosome 2 (70,257,386 to 70,281,185, forward strand). Ensembl gene ENSG00000116005.
Subcellular location: Lysosome
Gene Ontology:
Molecular function: FAD binding; farnesylcysteine lyase activity; prenylcysteine oxidase activity; protein binding; oxidoreductase activity, acting on a sulfur group of donors, oxygen as acceptor
Biological process: prenylated protein catabolic process; prenylcysteine catabolic process
Cellular component: extracellular exosome; lysosome; very-low-density lipoprotein particle
Genetic constraint (gnomAD): Loss-of-function variants: 33 observed, 31.46 expected, observed/expected ratio (o/e) 1.05, 90% interval 0.79 to 1.4. The upper end of that interval is the gene's LOEUF score, 1.4, which puts it in group 5 of 6, group 1 being the genes least tolerant of losing a copy. Missense variants: 505 observed, 487.16 expected, observed/expected ratio (o/e) 1.04, 90% interval 0.96 to 1.12. Synonymous variants: 172 observed, 181.7 expected, observed/expected ratio (o/e) 0.95, 90% interval 0.83 to 1.07.
Homologues: Orthologues: chimpanzee PCYOX1 (99% identical), macaque PCYOX1 (98% identical), rabbit PCYOX1 (86% identical), dog PCYOX1 (85% identical), guinea pig PCYOX1 (83% identical), mouse Pcyox1 (79% identical), pig PCYOX1 (78% identical), rat Pcyox1 (77% identical), tropical clawed frog pcyox1 (56% identical), zebrafish pcyox1 (51% identical). Paralogues in human: PCYOX1L (42% identical).
Diseases named in the same sentence as PCYOX1 in open-access papers:
PCYOX1 is named in the same sentence as 17 diseases in open-access papers, as found by Europe PMC text mining. Sharing a sentence is not in itself a finding about the gene and the disease. The quoted sentences say what the papers report.
atherosclerosis (6 papers, 2021 to 2024). A disease characterized by the build-up of fatty material and calcium deposition in the arterial wall resulting in partial or complete occlusion of the arterial lumen. "They find that loss of PCYOX1 is anti-atherogenic and understanding its biology and functions can potentially provide significant therapeutic opportunities in addressing atherosclerosis." (PMID 34548610, 2021). "PCYOX1 has recently emerged as a lipoprotein-associated protein, representing a potential novel member in the panel of oxidant enzymes involved in the pathogenesis of atherosclerosis." (PMID 35269975, 2022). "Mechanistically, it remains to be addressed whether reduced atherosclerosis associated with Pcyox1 deficiency could be the result of systemic changes in adipose tissue and lipid–glucose metabolism." (PMID 34548610, 2021). "Vasorin plays a role in arterial response to injury and PCYOX1 is a pro-oxidant enzyme known to be involved in heightened oxidative stress, tissue inflammation, and thickening/hardening of the arteries of atherosclerosis." (PMID 38673938, 2024). "In conclusion, PCYOX1 has biological functions that extend beyond its fundamental role in the prenylation process, with contributions to inflammation, thrombosis, and atherosclerosis." (PMID 34548610, 2021). "The observation that Pcyox1 deficiency in Apoe−/− mice fed with HFD, a model of obesity-accelerated atherosclerosis accompanied by development of a metabolic syndrome phenotype, have less adipose tissue depots, led us to further investigate the role of PCYOX1 in adipogenesis." (PMID 36978789, 2023). "Our study suggests that PCYOX1 might represent a novel member in the panel of oxidant enzymes involved in the pathogenesis of atherosclerosis." (PMID 34548610, 2021). "Collectively, these findings identify the pro-oxidant enzyme PCYOX1 as an emerging player in atherogenesis and, therefore, understanding the biology and mechanisms of all functions of this unique enzyme is likely to provide additional therapeutic opportunities in addressing atherosclerosis." (PMID 34548610, 2021). "We have recently shown that prenylcysteine oxidase 1 (PCYOX1) is a regulator of atherosclerosis-disease mechanisms, which acts through mechanisms not exclusively related to its pro-oxidant activity." (PMID 36978789, 2023). "PCYOX1 inhibition may be beneficial for mitigating the H2O2-triggered oxidation of phospholipids within lipoproteins, potentially opening new therapeutic avenues for cardiovascular diseases like atherosclerosis." (PMID 39322016, 2024). "Furthermore, we generated a double knockout mouse model (Pcyox1−/−/Apoe−/− mice) for studying the role of PCYOX1 in atherosclerosis, and PCYOX1 analysis by IHC and ISH was also performed on aortic root sections of Pcyox1+/+/Apoe−/− and Pcyox1−/−/Apoe−/− mice on high-fat diet (HFD) for 8 weeks." (PMID 34548610, 2021). "Finally, since PCYOX1 was not reduced in vitro by both fibrate and statin treatment, our results indicate that PCYOX1 might represent an additional drug target in atherosclerosis." (PMID 34548610, 2021).
Arterial thrombosis (3 papers, 2022 to 2024). The formation of a blood clot inside an artery. "The loss of Pcyox1 could cause platelet hypo-reactivity or impairment of arterial thrombosis, and Pcyox1 might be developed as an antithrombotic drug." (PMID 37076891, 2023). "PCYOX1, a recently identified protein, is involved in thrombosis, and its absence leads to platelet hyporesponsiveness and arterial thrombosis." (PMID 39176081, 2024). "We can simply hypothesize that the presence of PCYOX1 might affect functions and/or composition of soluble factors or macromolecules, such as lipoproteins, that play a role in arterial thrombosis." (PMID 35269975, 2022). "Although further studies are needed to understand which plasma component could be responsible of the different behaviour of platelets isolated from WT and Pcyox1−/− mice, Prenylcysteine Oxidase 1 may represent a promising target in the prevention and treatment of arterial thrombosis." (PMID 35269975, 2022).
COVID-19 (2 papers, 2022 to 2025). A disease caused by infection with severe acute respiratory syndrome coronavirus 2. "The lower levels of PCYOX1 protein seen in the COVID-19 groups may contribute to the liver dysfunction associated with COVID-1972." (PMID 35842456, 2022).
thrombosis (2 papers, 2022 to 2023). "Pcyox1 can be expressed in vascular and blood cells, and the lack of Pcyox1 brought about platelet hypo-reactivity as well as impaired arterial thrombosis." (PMID 37076891, 2023). "In this study we have shown for the first time that PCYOX1 is a critical modulator of arterial thrombosis as provided by the impressive low thrombotic phenotype here observed in Pcyox1−/− mouse under both models of thrombosis." (PMID 35269975, 2022). "Our findings show that the absence of PCYOX1 results in platelet hypo-reactivity and impaired arterial thrombosis, and indicates that PCYOX1 could be a novel target for antithrombotic drugs." (PMID 35269975, 2022).
Hepatic steatosis (1 paper, 2025). Steatosis is a term used to denote lipid accumulation within hepatocytes. "While direct evidence linking PCYOX1 to liver fat is lacking, its role in oxidative stress, lipid metabolism and inflammation points to a role in hepatic steatosis." (PMID 40004184, 2025).
insomnia (1 paper, 2025). A sleep disorder characterized by difficulty in falling asleep and/or remaining asleep. "The identification of PCYOX1 protein levels as a top hit for chronotype, and SMAD5 expression for insomnia, nominates these genes as high-priority candidates for understanding sleep–wake regulation." (PMID 41296471, 2025).
Obesity (1 paper, 2023). Accumulation of substantial excess body fat. "Overall, these data identify PCYOX1 as a master regulator and potential therapeutic target in obesity-related diseases." (PMID 36978789, 2023).
Stroke (1 paper, 2024). Sudden impairment of blood flow to a part of the brain due to occlusion or rupture of an artery to the brain. "With this background, the decrease in ApoB and PCYOX1 observed in HT-treated stroke patients could be considered as indicative of an atheroprotective effect of HT." (PMID 38732018, 2024).
cardiovascular disease (2 papers, 2024 to 2025). "Increased PCYOX1 activity results in higher levels of the pro-atherogenic oxidized LDL, a novel biomarker of cardiovascular disease." (PMID 40004184, 2025).
PCYOX1 also shares sentences with these, for which no sentence is quoted: liver disease (2 papers); tumor (2); degenerative diseases (1); gestational diabetes mellitus (1); Insulin resistance (1); liver dysfunction (1); metabolic syndrome (1); myotonic dystrophy (1).